TMEM258 (transmembrane protein 258)
Description:
Subunit of the oligosaccharyl transferase (OST) complex that catalyzes the initial transfer of a defined glycan (Glc(3)Man(9)GlcNAc(2) in eukaryotes) from the lipid carrier dolichol-pyrophosphate to an asparagine residue within an Asn-X-Ser/Thr consensus motif in nascent polypeptide chains, the first step in protein N-glycosylation. N-glycosylation occurs cotranslationally and the complex associates with the Sec61 complex at the channel-forming translocon complex that mediates protein translocation across the endoplasmic reticulum (ER). All subunits are required for a maximal enzyme activity. Involved in ER homeostasis in the colonic epithelium (By similarity).
Synonyms: C11orf10; Kuduk; Kud
Tractability: Small molecule: a structure with a bound ligand is known. Antibody: UniProt predicts a signal peptide or a membrane-spanning region; the Human Protein Atlas places it where antibodies can reach. PROTAC: its protein half-life has been measured.
Gene: Protein-coding gene on chromosome 11 (61,768,501 to 61,792,802, reverse strand). Ensembl gene ENSG00000134825.
Subcellular location: Membrane; Endoplasmic reticulum; Cytoplasm
Subcellular location (Human Protein Atlas): Cytosol; Plasma membrane
Pathways (Reactome):
Disease: Maturation of DENV proteins; Maturation of spike protein
Cell-Cell communication: Regulation of CDH1 posttranslational processing and trafficking to plasma membrane
Immune System: PD-L1(CD274) glycosylation and translocation to plasma membrane
Metabolism of proteins: Asparagine N-linked glycosylation
Gene Ontology:
Molecular function: protein binding; oligosaccharyltransferase complex binding
Biological process: protein N-linked glycosylation; protein secretion; response to endoplasmic reticulum stress
Cellular component: cytoplasm; endoplasmic reticulum; membrane; oligosaccharyltransferase complex; oligosaccharyltransferase complex A; oligosaccharyltransferase complex B; endoplasmic reticulum membrane
Genetic constraint (gnomAD): Loss-of-function variants: 11 observed, 10.43 expected, observed/expected ratio (o/e) 1.06, 90% interval 0.66 to 1.7. The upper end of that interval is the gene's LOEUF score, 1.7, which puts it in group 6 of 6, group 1 being the genes least tolerant of losing a copy. Missense variants: 81 observed, 104.1 expected, observed/expected ratio (o/e) 0.78, 90% interval 0.65 to 0.94. Synonymous variants: 40 observed, 40.8 expected, observed/expected ratio (o/e) 0.98, 90% interval 0.76 to 1.28.
Homologues: Orthologues: chimpanzee TMEM258 (100% identical), guinea pig TMEM258 (100% identical), macaque TMEM258 (100% identical), mouse Tmem258 (100% identical), pig TMEM258 (100% identical), rabbit TMEM258 (100% identical), tropical clawed frog tmem258 (97% identical), zebrafish tmem258 (92% identical), rat Tmem258l3 (89% identical), Drosophila melanogaster kud (65% identical), Caenorhabditis elegans tmem-258 (53% identical).
Diseases named in the same sentence as TMEM258 in open-access papers:
TMEM258 is named in the same sentence as 14 diseases in open-access papers, as found by Europe PMC text mining. Sharing a sentence is not in itself a finding about the gene and the disease. The quoted sentences say what the papers report.
dyslipidemia (4 papers, 2017 to 2020). "Among these potential candidate genes, there are six genes (CETP, APOB, TMEM258, FADS2, FADS1, and PVRL2) associated with all phenotypes of dyslipidemia." (PMID 32425817, 2020). "For example, TMEM258, a gene for adipose tissue regulation, was not identified by any previous GWAS studies for type 2 diabetes and obesity, but was one of the novel pleiotropic candidate genes for type 2 diabetes, obesity and dyslipidemia identified in this study." (PMID 30110382, 2018).
depression (2 papers, 2025). "Suggestive colocalisation was identified between TMEM258 and anxiety and between MYRF and depression (PP.H4 ≥ 0.6)." (PMID 40457327, 2025).
type 2 diabetes (2 papers, 2018 to 2022). "We used the ‘insulin secretion’ pPS of variants in eight genes associated with type 2 diabetes risk due to poor beta cell function: MTNR1B, HNF1A, GCK, TCF7L2, TMEM258, ADCY5, SLC3OA8 and ABO." (PMID 35247066, 2022).
Crohn disease (1 paper, 2016). A gastrointestinal disorder characterized by chronic inflammation involving all layers of the intestinal wall, noncaseating granulomas affecting the intestinal wall and regional lymph nodes, and transmural fibrosis. "rs102275, an intronic variant in TMEM258 associated with Crohn’s disease, is an eQTL for FADS2 in all cell types examined." (PMID 27015630, 2016).
immune disease (1 paper, 2022). "Among those, six gene knockouts resulted in an immune disease, including Cd28, Ndfip1, Skap2, Tmem258, Tnfrsf1a, and Tnfrsf9." (PMID 35591976, 2022).
tumor (1 paper, 2023). "Additionally, numerous studies have shown that TMEM123 and TMEM66 in T cells, and TMEM208, TMEM59, and TMEM258 in B cells, are closely related to inflammatory response and participate in tumor immune response, which is consistent with our findings." (PMID 37265785, 2023).
TMEM258 also shares sentences with these, for which no sentence is quoted: bipolar disorder (2 papers); Anxiety (1); asthma (1); Astigmatism (1); Hyperglycemia (1); Obesity (1); spinocerebellar ataxia (1); xeroderma pigmentosum (1).